AHR (aryl hydrocarbon receptor)
Diseases named in the same sentence as AHR in open-access papers (continued):
Sharing a sentence is not in itself a finding about the gene and the disease.
asthma (continued). "Second, previous studies have shown significant increases in AHR to bronchoconstriction agents in a mouse model of OVA-induced asthma." (PMID 29882826, 2018). "Targeting of CXCL1 or its receptor CXCR2 with blocking antibodies was recently shown to reduce AHR and goblet cell metaplasia in a murine asthma model." (PMID 27621809, 2016). "Curcumin, a dietary AhR compound found in turmeric, attenuates inflammation in asthma and systemic lupus erythematosus by regulating the induction of Tregs." (PMID 27445434, 2016). "This inflammation and AHR was sensitive to treatment with systemic steroids showing the model to be relevant to clinical asthma." (PMID 27112462, 2016). "Clarification of the interaction between AhR and PPARγ signals should broaden our understanding not only of the functional role of eosinophils but also of asthma regulation." (PMID 22500183, 2012). "We reviewed studies on the relationship between AhR function and airway inflammation, as it is important in the initial phase of asthma/COPD." (PMID 22500183, 2012). "This review discusses the role of AhR in asthma and COPD, focusing in particular on inflammatory and resident cells in the lung." (PMID 22500183, 2012). "Understanding the effects of AhR on these cells would be a breakthrough in our understanding of the pathology and treatment of asthma and COPD." (PMID 22500183, 2012). "The IL-1β has also been shown to induce aryl hydrocarbon receptor in murine model of asthma, in a dose and time-dependent manner." (PMID 23226977, 2012). "In children (outside a research setting) testing for AHR is reliably performed only in older children (>6 years) and positive AHR especially to direct AHR challenges as an indicator of asthma has questionable validity." (PMID 16270937, 2005). "In adults, tests for AHR are relatively easy to perform and direct AHR (methacholine, histamine) is used to exclude asthma." (PMID 16270937, 2005). "Additionally, PM exposure has been shown to alter the Treg/Th17 cell balance, aggravating asthma manifestations in an aryl hydrocarbon receptor (Ahr)‐dependent manner." (PMID 40497455, 2025). "In environmentally mediated inflammatory and respiratory diseases, AhR activation by PAHs disrupts mucosal barriers through oxidative stress and inflammation, leading to tissue damage in chronic obstructive pulmonary disease and asthma." (PMID 40559961, 2025). "Moreover, use of specific NLRP3 inflammasome inhibitors reduced HDM-induced AHR and attenuated steroid-resistant asthma in a mouse model." (PMID 38811424, 2024). "Taken together, AhR is the most important mediator of phthalates, suggesting that it could be a therapeutic target for phthalate‐aggravated asthma." (PMID 37315181, 2023). "Recent studies have revealed that IFNγ could up-regulate and down-regulate the expression of CXCL10 and SLPI, respectively, which further resulted in increased AHR and steroid resistance in severe asthma." (PMID 35187081, 2022). "This, taken together with the changes in AHR seen in male mice, suggests that leptin may play a greater role in modulating asthma outcomes in males compared to females." (PMID 35610699, 2022). "These include genes involved in oxidative stress responses and AhR signaling/detoxification, pro-inflammatory responses and alarmins, and tissue damage and repair, many of which are known to contribute to airway inflammation in asthma." (PMID 35627266, 2022). "have also reported that AhR−/− mice had exacerbated ovalbumin (OVA)–induced asthma symptoms, including airway inflammation, mucus production, and airway remodeling, and suggested that AhR is required in maintaining normal lung function and mediating disease severity." (PMID 35935956, 2022). "However, despite these limitations, these exposure regimes allowed us to compare the role of the AhR using two models of exposure that induce different asthma phenotypes." (PMID 34744763, 2021).
asthma (continued). "Thus, although the AhR controls immune cell infiltration to the lungs in the OVA asthma model, the AhR exerts minimal influence on airway function." (PMID 34744763, 2021). "In the irritant-induced asthma model caused by exposure to Cl2, the AhR did not regulate the inflammatory response." (PMID 34744763, 2021). "Thus, we show that AhR differentially affects the development asthma-like disease, with the majority of AhR-dependent effects involving the suppression of inflammation associated with the allergic phenotype." (PMID 34744763, 2021). "We next utilized a model of irritant-induced asthma that provokes a neutrophilic response in the lungs and airways to evaluate whether the AhR can also suppress neutrophilia in response to diverse etiologic agents." (PMID 34744763, 2021). "Recently, a role of the AhR in regulating allergic asthma has been suggested, but whether the AhR also regulates other type of asthma, particularly occupational/irritant-induced asthma, remains unknown." (PMID 34744763, 2021). "Our previous studies have suggested that AhR controls mast cell growth and activation, cockroach allergen-induced immune responses in human fibroblast, and allergic airway inflammation in a mouse model of asthma." (PMID 33936062, 2021). "Thus, a reduced AHR content is frequently found in people with chronic exposure to exogenous AHR ligands and is accompanied by a series of pathologies, including asthma, chronic obstructive pulmonary disease (COPD), and lung cancer." (PMID 34576152, 2021). "Taken together, these findings indicate that RhoA/Rho‐kinase signalling shows promise for AHR, suggesting that RhoA/Rho‐kinase may be a potential therapeutic target for severe asthma." (PMID 32355562, 2020). "Mfge8‐deficient mice (Mfge8−/−) developed exaggerated AHR in an experimental asthma model, suggesting that Mfge8 may protect against the exaggerated AHR." (PMID 32355562, 2020). "Chronic exposure to IP, a prominent ambient PAH, may affect DC functions through modulating AhR activity, leading to enhanced allergic inflammation in an established asthma murine model." (PMID 29581487, 2018). "Previous studies have demonstrated that the chemotactic migration of DCs also plays an important role in the immune pathogenesis of asthma; thus, whether AhR activation disturbs the chemotactic migration of DCs requires further investigation." (PMID 26938767, 2016). "Therefore, in an allergic model of asthma, myriocin‐treatment is associated with enhanced HDM‐induced AHR and an altered goblet cell gene expression pattern." (PMID 27621809, 2016). "HCB has also been reported to show some agonist activity with the AhR, which suggests that HCB might affect the immune system and asthma through AhR-mediated mechanisms." (PMID 24162035, 2014). "We describe the important impact that AhR activation may have on the inflammation phase in the pathology of asthma and COPD." (PMID 22500183, 2012). "In addition, AhR expression in splenic B cells was enhanced by the presence of lipopolysaccharide, which is known to exacerbate asthma and COPD." (PMID 22500183, 2012). "Furthermore, recent studies suggest that several AhR-activating compounds affect the immune response in a beneficial way by inhibiting symptoms of allergies and asthma." (PMID 17450213, 2007). "Additionally, these four tryptophan metabolites, particularly IAA, could enhance tryptophan metabolism in the gut and increase the production of tryptophan metabolites, which can further bind to AhR to alleviate asthma." (PMID 38731707, 2024). "The activation of ADRB2 on human peripheral blood lymphocytes enhances IL-13 production, and studies have found that ADRB2 is required for mucus metaplasia, AHR and lung inflammatory cells in asthma models, and that the prolonged use of ADRB2 blockers could relieve allergic asthma." (PMID 36389706, 2022).
asthma (continued). "However, the regulation of AhR on these identified autophagy genes and the exact role of these genes in the pathogenesis of asthma remain unclear, thus warranting further, in-depth investigations." (PMID 35935956, 2022). "Thus, the functional axis of AhR-ROS-NLRP3 inflammasome could lead to new therapeutic perspectives for asthma." (PMID 34868022, 2021). "Through the augmenter of KC (keratinocyte-derived chemokine) and MIP-2 (macrophage inflammatory protein-2), the asthma-like inflammation, including phenotypic changes like increased inflammatory cells, mucin production, and AHR, could be significantly deteriorated." (PMID 32411804, 2020). "Recent data have shown that AhR is critical for a wide range of immune functions including the maintenance of innate and adaptive cell populations at mucosal barrier sites, and the control of inflammation at steady-state or during ongoing inflammatory responses, such as asthma." (PMID 33233810, 2020). "Thus, we hypothesized that TCDD-induced activation of AhR may play an immunoregulatory role in airway inflammation in asthma." (PMID 26938767, 2016). "Therefore, we hypothesized that DEP-PAH, and some purified PAH previously shown to be involved in asthma, might affect, through their effects on AhR, IL-17 and IL-22 cytokine profiles." (PMID 25860963, 2015). "The expression levels of FCER1A and TLR‐9 in IL‐5‐ or IL‐17‐activated eosinophils and those of aryl hydrocarbon receptor and TLR‐7 in IL‐5‐activated eosinophils were significantly higher for patients with asthma than for normal individuals." (PMID 39575691, 2024). "Thus, these four pure tryptophan metabolites, especially IAA, could promote microbial tryptophan metabolism and the production of tryptophan metabolites, further activating and binding to AhR, thereby improving intestinal barrier integrity, and ultimately alleviating asthma." (PMID 38731707, 2024). "We previously showed that increased IL-1β responses drive steroid-insensitive, inflammation and AHR, and that inhibiting NLRP3 activation with MCC950 reduced IL-1β production and ablated these features in murine models of severe asthma." (PMID 38044426, 2023). "Finally, the inhibitory effects of siRNA for AhR and its antagonist on epithelial cells were evaluated because of airway epitheliums are the first contact cells when exposed to phthalates and they can orchestrate airway inflammation in the pathogenesis of asthma." (PMID 37315181, 2023). "In our study, AHR significantly increased in the OVA and OVA-LPS sensitized asthma groups compared to healthy control animals (p < 0.05)." (PMID 35296330, 2022). "In bronchial epithelial cells, AhR agonists led to the upregulation of MMP2, MMP9, and MMP1 and proposed to contribute to airway remodeling in asthma and chronic obstructive pulmonary disease." (PMID 33488929, 2020). "However, apigenin treatment reduced all asthma features, such as AHR, airway inflammation, type 2 cytokines, and the expression of the aryl hydrocarbon receptor in MnBP‐augmented eosinophilic asthma." (PMID 37315181, 2023). "By contrast, AhR expression was found in both epithelial and hematopoietic human lung cells irrespective of an asthma background." (PMID 35734174, 2022). "Not surprisingly, AhR has emerged as an attractive therapeutic target for different diseases including asthma." (PMID 35935956, 2022). "Furthermore, we found a co-localization between AhR and RhoA-GTP in the airways of an asthma mouse model, indicating a possible interaction between AhR and RhoA-GTP." (PMID 33936062, 2021). "Therefore, all these results indicate that DTA‐64 can reduce OVA‐induced asthma by reducing goblet cell hyperplasia, TGF‐β1 expression, serum IgE and AHR." (PMID 33124760, 2020). "Taken together, MMPs from IL-17A-mediated inflammation via the AhR activation induced by cigarette smoke exposure may thus contribute to neo-osteogenesis and recalcitrant disease in patients with CRS and asthma." (PMID 31653934, 2019).
asthma (continued). "The lack of AHR in many of the RA subjects suggests that the AHR resolves in many subjects in which asthma symptoms resolve." (PMID 23043798, 2012). "There are already a few approved pharmaceuticals that likely function via the AHR (including treatments for asthma and organ rejection), but none that combines the effect of VEGF blockade with modulation of the AHR." (PMID 22970246, 2012). "Although, the AhR mitigates allergic asthma, whether the AhR affects the pathogenesis of other types of asthma, such as irritant-induced asthma, was not known." (PMID 34744763, 2021). "In a murine cockroach allergen (CRE)-induced asthma model, the injection of BM-MSC modulate macrophage differentiation from a pro-inflammatory phenotype (M1) to an anti-inflammatory phenotype (M2), apparently by aryl hydrocarbon receptor (AhR) signaling activation." (PMID 33959015, 2021). "AHR activation in some immune cells favors the anti-inflammatory phenotype, and AHR-related epigenetic regulation involving the ten-eleven translocation 1 (TET1) methylation alleviates interferon activation, protecting bronchial epithelial cells against asthma features." (PMID 34576152, 2021). "However, since protease-depleted GC frass decreased AHR and mucin production in wild type mice similar to our findings with the PAR-2 backcrossed mice, we feel that it is unlikely that our effects are due solely to asthma genes surrounding the PAR-2 locus." (PMID 20497568, 2010). "Therefore, although Th17 plays a role in regulating neutrophil and macrophage inflammation, it is not known whether IL-17 induced by AhR activation contributes to the development of asthma or COPD." (PMID 22500183, 2012). "It is likely that the intrinsic AHR evident in the SAA3−/− mice obscures their response to methacholine after HDM challenge, and differences between wild type and SAA3−/− mice are not apparent in this robust, acute model of asthma." (PMID 30410021, 2018).
Hepatic steatosis (79 papers, 2012 to 2025). Steatosis is a term used to denote lipid accumulation within hepatocytes. "PCB serves as a classical ligand for the aryl hydrocarbon receptor (AhR), and the activation of this transcription factor is associated with the exacerbation of hepatic steatosis." (PMID 39133714, 2024). "On the contrary, AHR activation in rodents by environmental contaminants is associated with spontaneous hepatic steatosis characterized by the accumulation of triglycerides, cholesterol biosynthesis impairments and systemic metabolic dysfunction." (PMID 34418449, 2022). "Based on the analysis of our transcriptome data, 23 transcription factors were identified, and the transcription factor AHR was identified as one of the top hits, which has been linked to hepatic steatosis in previous reports." (PMID 34803486, 2021). "It is interesting to note that environmental toxins which activate the ARNT-partner aryl hydrocarbon receptor are associated with fatty liver disease." (PMID 31800592, 2019). "Findings from AHR-deficient mice show that, like GF mice, they are protected from high fat diet-induced obesity, hepatic steatosis, and insulin resistance." (PMID 27858116, 2017). "To explore the mechanism of AHR involvement in hepatic steatosis caused by GHR deletion, we used Co-IP experiments to verify whether there is a protein interaction between AHR and GHR." (PMID 34803486, 2021). "Supplementing with AhR agonists and ligands can lead to improvements in metabolic disorders, including inflammatory responses and hepatic steatosis." (PMID 41273480, 2025). "Restoration of AhR signaling mitigates metabolic disturbances, including glucose metabolism dysregulation and hepatic steatosis." (PMID 41440753, 2025). "Extensive studies have demonstrated that upon exposure to environmental pollutants (e.g., TCDD, BaP, HCB), the activation of the AhR significantly drives the initiation and progression of hepatic steatosis through a synergistic, multi-target network." (PMID 41585883, 2025). "AhR ligand 3-methylcholanthrene (3MC) also significantly increased the expression level of fatty acid translocase in liver by activating AhR, inducing hepatic steatosis." (PMID 39944639, 2025). "In conclusion, our study suggests that healthy gut microbiota transplantation ameliorated high-fat diet-induced liver steatosis and reversed decreased liver ILC1 induced by HFD associated with the level of indole-3-carbinol and AhR activation." (PMID 40046764, 2025). "Elimination of hepatic AhR significantly attenuated TCDD-induced hepatic steatosis, adipocyte hypertrophy, and macrophage infiltration." (PMID 40943373, 2025). "In summary, these results jointly demonstrate that the inhibition of AHR/MAPK9 mediated by tryptophan-ILA ligand depletion is both sufficient to ameliorate NAFLD-related hepatic steatosis and required for a High BCAA to maximally ameliorate metabolic health." (PMID 39426289, 2024). "Some studies examining the role of AhR in fatty acid metabolism and MASLD reported that TCDD-induced AhR activation resulted in hepatic steatosis and further inflammation and fibrosis." (PMID 38791241, 2024). "Our most striking finding was that tryptophan-ILA depletion induced by High BCAA feeding led to AHR/MAPK9-mediated hepatic steatosis and DNL downregulation." (PMID 39426289, 2024). "AhR agonists are known to decrease in cases of metabolic syndrome and fatty liver and administering AhR agonists to mice models has been found to reduce liver injury." (PMID 38191517, 2024). "Specific gestational deletion of AhR from the liver exacerbates metabolic disease conditions, such as hepatic steatosis in animals fed HFDs, whereas conditional knockout from adult liver helps ameliorate this pathology." (PMID 37443781, 2023). "Indole has shown to alleviate diet induced hepatic steatosis, and the hepatoprotection was dependent on the activation of the AhR signaling pathway." (PMID 37284280, 2023).